MUC4 (mucin 4, cell surface associated)
Diseases named in the same sentence as MUC4 in open-access papers (continued):
Sharing a sentence is not in itself a finding about the gene and the disease.
colon adenoma (1 paper, 2022). An adenoma that arises from the colon. "The complete loss or deletion of Muc4 in AMC mice was associated with a significant loss of Muc2 in the colon adenoma compared to normal mice." (PMID 35255004, 2022).
Constipation (1 paper, 2021). Infrequent or difficult evacuation of feces. "Consistent with that, the subjects recruited in this study all had symptoms of constipation, the SNVs identified in the samples were enriched in the genes associated with gut functions, e.g. the mucin gene (MUC2, MUC3A, MUC4, and MUC5B)." (PMID 33412999, 2021).
dermatofibrosarcoma protuberans (1 paper, 2024). Dermatofibrosarcoma protuberans (DFSP) is a rare infiltrating soft tissue sarcoma, generally of low grade malignancy, arising from the dermis of the skin and characteristically associated with a specific chromosomal translocation t(17;22). "Mutually exclusive mutations in MUC4 and MUC6 have been identified in dermatofibrosarcoma protuberans." (PMID 39338204, 2024).
desmoid tumor (1 paper, 2022). A desmoid tumor (DT) is a benign, locally invasive soft tissue tumor associated with a high recurrence rate but with no metastatic potential. "Besides the well-known CTNNB1, which was identified 100% mutation in our samples, we also identified several mutations, such as membrane-associated mucins (MUC4, MUC12), which may also play some role in the development and progression of pediatric desmoid tumors." (PMID 36539683, 2022).
endometrial cancer (1 paper, 2022). Primary or metastatic malignant neoplasm involving the endometrium (mucous membrane that lines the endometrial cavity). "Recently, it has been reported that IFN-γ can lead to EMT transition in pancreatic cells or endometrial cancer cells through the stimulation of MUC4 transcription, which is expressed in an aggressive or metastatic tumor phenotype by the activation of STAT1." (PMID 35283421, 2022).
enteritis (1 paper, 2016). Inflammation of the small intestine. "We recently found that an F4+ enterotoxigenic E. coli (ETEC)/verocytotoxigenic E. coli (VTEC)/enteropathogenic E. coli (EPEC) hybrid can cause enteritis and/or fever in MUC4 RR pigs." (PMID 27424033, 2016). "Our previous findings indicated that excessive generation of CD4+IL-10+ T cells induced by oral administration of BLS-mix to newly weaned MUC4 RR pigs with enteritis caused by an enteric pathogen might prohibit clearance of the pathogen." (PMID 27424033, 2016). "Efficient strategies for treating enteritis caused by F4+ enterotoxigenic Escherichia coli (ETEC)/verocytotoxigenic Escherichia coli (VTEC)/enteropathogenic E. coli (EPEC) in mucin 4 resistant (MUC4 RR; supposed to be F4ab/ac receptor–negative [F4ab/acR−]) pigs remain elusive." (PMID 27424033, 2016).
epithelioid mesotheliomas (1 paper, 2018). "MUC4 expression was not present in any of 65 epithelioid mesotheliomas (0%)." (PMID 29317712, 2018).
Fanconi anemia (1 paper, 2025). Fanconi anemia (FA) is a hereditary DNA repair disorder characterized by progressive pancytopenia with bone marrow failure, variable congenital malformations and predisposition to develop hematological or solid tumors. "In addition, GSEA analysis showed that MUC4 was enriched in Fanconi anemia, GnRH secretion, PPAR signaling, and other pathways; PELI2 was enriched in MAPK, Ras, Wnt, and other signaling pathways." (PMID 38536652, 2025).
fibromatosis (1 paper, 2023). A poorly circumscribed neoplasm arising from the soft tissues. "Superficial fibromatosis typically lacks myxoid stroma, has a more fascicular growth pattern, and is negative for MUC4." (PMID 36074249, 2023).
fibrosarcoma (1 paper, 2023). A malignant mesenchymal fibroblastic neoplasm affecting the soft tissue and bone. "More research is needed to determine the implications of this negative MUC4 expression in fibrosarcoma." (PMID 38156143, 2023). "In this case, the absence of MUC4 expression may indicate a distinct molecular profile or mechanism at work in the fibrosarcoma, which might have consequences for prognosis and therapy." (PMID 38156143, 2023).
fibrous tumor (1 paper, 2022). "Immunohistochemical stains for pan-cytokeratin, DOG1, desmin, S100, CD34, and MUC4 were negative, and a diagnosis of the calcifying fibrous tumor was rendered." (PMID 36186113, 2022).
gallbladder tumour (1 paper, 2022).
ganglioneuroma (1 paper, 2024). A benign neuroblastic tumor of the sympathetic nervous system that occurs in childhood. "The MUC4 variants p.Ser2666Tyr and p.Ser2661Gly have been reported in pediatric patients with ganglioneuromas." (PMID 39338204, 2024). "MUC4 has been reported to participate in the progression of ganglioneuromas." (PMID 39338204, 2024).
gastric disease (1 paper, 2023). "Studies of human samples revealed that metaplastic pit cells increase in abundance as gastric disease develops, and MUC4 expression is significantly associated with cell proliferation." (PMID 37674528, 2023).
hearing loss (1 paper, 2020). "Lastly, the MUC4 gene also was found to track with symptom of tinnitus in breachers, and has been previously implicated in mucoid otitis media (MOM) a common otological disease that can result in hearing loss." (PMID 33192958, 2020).
hepatoblastoma (1 paper, 2020). Hepatoblastoma (HB) is a malignant hepatic tumor and is the most common pediatric liver cancer. "For example, one study identified 6 ALL and 13 AML patients with a CH variant in KMT2C, and one study identified two hepatoblastoma patients with a CH variant in MUC4." (PMID 32508881, 2020).
intestinal infection (1 paper, 2020). "As differences in MUC4 genotypes appear to affect the composition of gastrointestinal microbiota, MUC4 polymorphisms have been proposed to play roles in intestinal infection, such as PWD." (PMID 32784676, 2020).
kidney chromophobe carcinoma (1 paper, 2025).
laryngeal carcinoma (1 paper, 2025). Carcinoma that arises from the laryngeal epithelium. "The mucin‐related genes, MUC1 and MUC4, are overexpressed in treatment‐resistant laryngeal carcinoma." (PMID 40385549, 2025). "We anticipate that by targeting mucin‐overexpressing laryngeal cancer cells, the chitosan‐coated liposomes will electrostatically bind to transmembrane mucins like MUC1, MUC4, MUC17 and thus enhance the drug intake and retention process." (PMID 40385549, 2025).
lung neoplasm (1 paper, 2017). A benign or malignant, primary or metastatic neoplasm involving the lungs. "Since MUC4 is a key mucin in pathological diagnosis of lung neoplasms, our goal is to apply DNA methylation analysis of this gene using bronchoalveolar lavage fluid and/or sputum for early diagnosis of lung neoplasms." (PMID 28680536, 2017). "As no recent study has evaluated the extent of 5hmC modification of the MUC4 gene and correlated this to expression levels of MUC4 mRNA in lung tumors, we analyzed MUC4 5mC status and/or 5hmC status in lung tissue to study the relationship between MUC4 promoter modification and expression." (PMID 28680536, 2017).
malignant glioma (1 paper, 2022). A grade III or grade IV glioma arising from the central nervous system. "MUC4 serum mean protein levels tended to be higher in the malignant glioma grades (grades III and IV) compared to the control samples, but the difference was not statistically significant (p-value = 0.42 and 0.92, respectively)." (PMID 36400876, 2022).
mammary adenocarcinoma (1 paper, 2004). "Nevertheless, the expression of MUC4 is also regulated by TGFβ2, post-translationally and post-transcriptionally in normal and mammary adenocarcinoma cells, respectively." (PMID 14760381, 2004).
mesenchymal chondrosarcoma (1 paper, 2024). A morphologic variant of chondrosarcoma arising from bone and soft tissue. "Of the tumors reclassified as mesenchymal chondrosarcomas (cases 14 and 16), CD99 was strongly positive in case 14, while SATB2, BCOR, and MUC4 were negative." (PMID 38332052, 2024).
nematode infection (1 paper, 2013). "In contrast to clearance of nematode infection, onset of clearance of C. rodentium was preceded by an early increase in Muc1, Muc2, Muc4 and Muc13 mucin transcript levels that had returned to pre-infection levels at least four days prior to clearance." (PMID 24386378, 2013).
Pancreatic cysts (1 paper, 2018). A cyst of the pancreas that possess a lining of mucous epithelium. "The second logistic regression model analysis was performed to predict MUC4 protein expression based on the type of pancreatic cyst." (PMID 34164227, 2018). "However, type of pancreatic cysts was predictive of MUC4 expression." (PMID 34164227, 2018). "No previous studies have investigated MUC4 expression in pancreatic cysts and our study is the first investigation of this possible association." (PMID 34164227, 2018). "Expression of MUC4 was not different between cancers and pancreatic cysts (p=0.16)." (PMID 34164227, 2018).
pancreatic disease (1 paper, 2014). "A predictive model for identification of pancreatic disease was constructed using the U-indexes of MUC1, MUC2 and MUC4 based on quadratic or canonical discriminant analysis." (PMID 24714692, 2014).
papillary carcinoma (1 paper, 2014). A malignant epithelial neoplasm characterized by a papillary growth pattern. "Further, complete loss of MUC4 expression was observed in both non-invasive and invasive cases of papillary carcinoma (N = 10, mean intensity 0.8±0.41; mean H-score 0.31±0.39)." (PMID 24671186, 2014). "Invasive papillary carcinoma (N = 2) showed complete loss of MUC4 expression (Intensity-score = 0)." (PMID 24671186, 2014).
Pleural effusion (1 paper, 2009). The presence of an excessive amount of fluid in the pleural cavity. "Based on these arguments, we would predict that MUC4 overexpression might be particularly prevalent in actively metastasizing cells such as circulating tumor cells, or in metastatic cells that accumulate in abdominal or pleural effusions." (PMID 19761616, 2009).
renal failure (1 paper, 2021). "Of particular interest is the strong correlation between mortality, renal failure, and MUC1 mRNA expression and between mechanical ventilation and MUC4 and MUC16 mRNA expression." (PMID 34448730, 2021).
sarcomatoid carcinoma of (1 paper, 2018). "In our previous report, we emphasized the MUC4 expression in spindled cells of sarcomatoid carcinoma of lung." (PMID 29317712, 2018).
sarcomatoid carcinoma of lung (1 paper, 2018). "MUC4 was expressed in 72% of the sarcomatoid carcinoma of lung." (PMID 29317712, 2018).
sarcomatoid mesothelioma (1 paper, 2018). A diffuse malignant mesothelioma arising from the pleura and less often the peritoneum. "None of sarcomatoid mesothelioma had the expression of MUC4 expression." (PMID 29317712, 2018).
SARS-CoV infection (1 paper, 2021). "A recent study has suggested that MUC4 expression plays a protective role in female mice in SARS-CoV infection." (PMID 34064525, 2021).
serous cystadenoma (1 paper, 2018). A serous neoplasm in which the cysts and papillae are lined by a single layer of cells without atypia, architectural complexity or invasion. "Mucinous cystic neoplasms and serous cystadenoma cysts showed significantly higher MUC4 expression than non-specified and pseudocysts (80%, 75%, 25%, and 0% expression for the 4 types of cysts, respectively) (p=0.022)." (PMID 34164227, 2018).
serous ovarian carcinomas (1 paper, 2016). "MUC16 is known to be expressed in most serous ovarian carcinomas and may function like MUC1 and MUC4 in tumor cell growth, motility and tumorogenicity." (PMID 26735499, 2016).
signet ring cell carcinoma (1 paper, 2008). A usually aggressive, poorly differentiated invasive adenocarcinoma characterized by the presence of malignant glandular cells in which the nucleus is pressed to one side by the presence of intracytoplasmic mucus. "Out of a total of 128 tissue spots, we found that the proportion of MUC4-positive staining is lower for normal adjacent spots (n=45, 9%) compared with patients with adenocarcinoma (n=58, 43%) and signet ring cell carcinoma (n=25, 32%) (P<0.001)." (PMID 18781152, 2008).
skin cutaneous melanoma (1 paper, 2022). "TTN, a potential skin cutaneous melanoma related marker, was co-mutated with MUC4 in HCC based on our analysis." (PMID 36081995, 2022).
small intestinal carcinoma (1 paper, 2014). "We also previously examined mucin expression in small intestinal carcinoma, and found positive expression rates of MUC1, 51.7%; MUC2, 26.7%; MUC3, 55.0%; MUC4, 51.7%; MUC5AC, 33.3%; MUC6, 10.0%; and MUC16, 8.3% (MUC17 expression was not examined)." (PMID 25551773, 2014).
thrombosis (1 paper, 2026). "In this study, we confirmed that MUC4 mutation is an independent risk factor for thrombosis in PNH patients." (PMID 41492103, 2026). "Complement deposition assays and a murine lower limb deep vein thrombosis model were used to investigate the role of MUC4 mutation in thrombotic risk and explore the underlying mechanism involving terminal complement activation in PNH patients." (PMID 41492103, 2026). "In our previous studies, we reported that some PNH patients with thrombosis had MUC4 mutations." (PMID 41492103, 2026). "To determine the relationship between MUC4 mutation/down‐regulation and TEs, we constructed a lower limb DVT model by ligating the unilateral iliac vein and compared the incidence of thrombosis and thrombus length among the WT, Muc4‐KO, Piga‐KO and Piga/Muc4‐DKO groups after surgery." (PMID 41492103, 2026). "We analyzed clinical data from PNH patients with or without thrombosis, including MUC4 mutation status and serum complement C5b‐9 levels." (PMID 41492103, 2026). "We further determined the expression levels of MUC4 in the PB leukocytes of PNH patients with acute TEs (PNH‐TE group) and PNH patients without thrombosis (PNH non‐TE group)." (PMID 41492103, 2026).
thyroid autoimmune disease (1 paper, 2021). "The MUC4 mutation revealed no pathway with an FDR q-value < 0.05, whereas the USH2A mutation featured the following significantly upregulated pathways: antigen processing and presentation pathways, thyroid autoimmune disease pathways, and NK cell-mediated cytotoxic pathways." (PMID 34795697, 2021).
Tinnitus (1 paper, 2020). Tinnitus is an auditory perception that can be described as the experience of sound, in the ear or in the head, in the absence of external acoustic stimulation. "Notably, we identified KCNN3, SOD3, MUC4, GALR1, and WDR45B, which are implicated in auditory function, as differentially methylated associated with self-reported tinnitus." (PMID 33192958, 2020). "Notably, tinnitus symptom analyses identified regions with differential methylation in genes KCNN3, MUC4, GALR1, SOD3, and WDR45B (in the low vs. high cumulative blast exposed groups." (PMID 33192958, 2020).
tumor (266 papers, 2001 to 2025). "Findings further indicate that MUC4 is closely linked to lymphatic and vascular invasion, thereby positioning it as a potential biomarker for aggressive tumor behavior." (PMID 40655139, 2025). "TFag is a TACA that is found primarily in tumors and has been shown to be present on tumor-associated MUC4 proteins." (PMID 40649822, 2025). "Aberrant glycosylation is also a tumor-associated feature of the MUC4 protein, and certain TACAs are known to be present in the TR region." (PMID 40649822, 2025). "Excessive MUC4 expression is strongly associated with poor differentiation, advanced tumor stage, and high ErbB2 expression." (PMID 40655139, 2025). "The calculation results of KM analysis showed that the USH2A mutation and MUC4 mutation were related to tumor survival and prognosis." (PMID 34795697, 2021). "MUC4 expression in cancer is also associated with poor prognosis of the tumor and poorer overall survival of patients, which makes it a potent prognostic biomarker." (PMID 34830899, 2021). "The mutation frequencies of Akap9, Cdh11, and Muc4 are less than 7% in the TCGA tumor database, whereas their mutation rates are higher than 85% in the murine OSCC cell lines analyzed." (PMID 33302499, 2020). "Conversely, some genes are associated with both tumor status and survival (MUC4 for HNSC, TMPRSS11F, SLC6A18, and DEFB119 for LGG)." (PMID 32625238, 2020). "The current studies provides a basis for investigating the use of the MUC4β-nanovaccine as an immunotherapeutic strategy in cancer models that overexpress MUC4 as a tumor-associated antigen." (PMID 31258832, 2019). "In detail, mutations in two distinct genes were associated with radiomic features: in the BAP1 gene, associated with ill-defined tumor margins and with the presence of calcification, and in the MUC4 gene, associated with exophytic growth." (PMID 31795520, 2019). "Recently, a meta-analysis based on 1900 patients from 18 studies showed that MUC4 overexpression was associated with tumor stage, tumor invasion and lymph node metastasis." (PMID 30236127, 2018). "The mutation accumulation in trunk genes, especially VHL and MUC4, can regulate cell adhesion, helping tumor cells to escape from the immune system." (PMID 29463849, 2018). "Downregulated MUC4 has been reported to induce tumor progression in conjunction with an EGFR mutation." (PMID 30404194, 2018). "MUC4 encodes an integral membrane glycoprotein found on the cell surface and plays a role in tumor progression." (PMID 29262625, 2017). "Each of the three genes (RHPN2, MUC4 or ADAM21) that harbored mutations in more than one tumor has a regulatory role in cell adhesion and motility, cell functions essential to the metastatic process." (PMID 29259192, 2017). "MUC4 promotes intestinal cell proliferation during tumorigenesis, and mice deficient in MUC4 exhibited reduced tumor burden compared with WT mice." (PMID 27829225, 2017). "Among various family members, MUC1 and MUC4 are implicated in tumor growth, intracellular and extracellular signaling, tumor–stromal interactions, metastasis, and resistance to chemotherapeutic agents and in immunity." (PMID 24671186, 2014). "Aberrant MUC4 overexpression is associated with invasive tumor proliferation and poor outcome in epithelial cancers." (PMID 24204934, 2013). "In contrast, the HPV-positive tumor had five mutations in four different mucin genes, including the secreted Muc6, and the transmembrane bound Muc4, Muc12 and Muc16." (PMID 23304554, 2012). "Several variants of human MUC4 have been reported from mainly tumour tissues and transcript variants 1, 4 and 5 are commonly observed." (PMID 21718470, 2011). "Recent studies have shown that MUC4 is implicated in modulation of ErbB2 signalling, in repression of apoptosis, in regulation of cell adhesion, in promoting tumor progression and metastasis, and in multidrug resistance processes." (PMID 20553613, 2010).